PAK4 (p21 (RAC1) activated kinase 4)
Diseases named in the same sentence as PAK4 in open-access papers (continued):
Sharing a sentence is not in itself a finding about the gene and the disease.
breast cancer (continued). "For example, PAK4 is up-regulated in most human cancer cell lines, and has also been found to be overexpressed in patient material of several human cancer forms, including colon, esophageal, pancreas, ovarian cancer, and breast cancer." (PMID 26554417, 2015). "Based on the prognostic role of PAK4 in endocrine treated and tamoxifen-only treated breast cancer patients, we examined if PAK4 may affect the tamoxifen response in human breast cancer cells." (PMID 26554417, 2015). "Together, this indicates that PAK4 contributes to tamoxifen resistance in breast cancer cells and may be used as a target to restore tamoxifen sensitivity." (PMID 26554417, 2015). "The idea that both Pak1 and Pak4 could have roles in breast cancer has very important implications in the future drug development." (PMID 23326684, 2012). "We have uncovered a previously unknown signaling pathway implicating p21-activated kinase 4 (PAK4) in the control of senescence in breast cancer, via the nuclear factor kappa-light-chain-enhancer of activated B cells (NF-κB) subunit RELB and the CCAAT-enhancer-binding protein beta (C/EBPβ)." (PMID 32158912, 2020). "Based on this and on our findings that PAK4 inhibition restored senescence in breast cancer, PAK4 inhibition may be explored as a potential therapeutic strategy for breast cancer, the most frequently diagnosed cancer in women world-wide and one of the major causes of lethality." (PMID 32158912, 2020). "However, our understanding of the in vivo function of PAK4 in breast cancer remains limited." (PMID 31594963, 2019). "Because PAK4 nuclear localization correlates with the development of ERα-negative phenotypes, leading to increased metastasis to the bone, searching for therapeutic strategies to block the entry of PAK4 into the nucleus would be useful for preventing breast cancer metastasis in ERα+ breast cancer." (PMID 30177834, 2019). "To further assess the function of PAK4 during mammary cancer development, we generated an additional genetically engineered mouse based on the widely used and relevant Polyoma Middle T (PyMT) transgenic breast cancer mouse model that is in part driven by PyMT-induced RAS signaling." (PMID 31399573, 2019). "The accumulated information suggests that PAK4 might be an oncogenic protein in breast cancer." (PMID 28407679, 2017). "However, the potential role of PAK4 in breast cancer remains largely elusive, for example whether PAK4 may directly affect breast cancer related proteins such as ERα." (PMID 26554417, 2015). "Also, in relation to the PAK4 expression level correlation with patient outcome, it should be noted that PAK4 in breast cancer may play other or additional roles to tamoxifen resistance that may influence that patient outcome." (PMID 26554417, 2015). "In addition to Pak4, other Pak family members are also overexpressed in breast cancer, particularly Pak1.14, 15, 16, 17, 18, 19, 20 Pak4 appears to be unique, however, in that wild-type Pak4 alone is sufficient to cause tumorigenesis in mice when overexpressed." (PMID 23732710, 2013). "Overexpressed PAK4 enhanced proliferation, migration, and invasion in MDA-MB-231 breast cancer cells by activating the PI3K/AKT pathway." (PMID 39337621, 2024). "Among the diabetes-related genes, FOXA1, MTA3, PAK4, FGFR3, and KIF22 were highly expressed in HR+ breast cancer from 4032 breast cancer patient tissue samples using the Breast Cancer Gene Expression Omnibus." (PMID 39000600, 2024). "As FOXA1 had the most significant gene expression, we checked the correlation between FOXA1 and other diabetes-related genes such as PAK4, FGFR3, MTA3, and KIF22 using a database containing 3262 ER+/PR+ breast cancer patient tissue samples." (PMID 39000600, 2024). "A higher expression of PAK4 promoted proliferation and invasiveness through activation of the PI3K/AKT pathway in breast cancer cells and through c-Src and the EGFR pathway in ovarian cancer cells." (PMID 36980457, 2023).
breast cancer (continued). "Suppression of PAK4 was also found to mitigate activation of the PI3K/AKT pathway and inhibited progression of breast cancer." (PMID 36105226, 2022). "Collectively, our study reveals the therapeutic effectiveness of ORFV on breast cancer and highlights the potential application of ORFV in combination with PAK4 inhibitors in cancer treatment." (PMID 35401439, 2022). "The CRISPR-Cas9 knockout library targeting 507 kinases was used to screen out PAK4, which is beneficial to the anti-tumor effect of ORFV on breast cancer cells." (PMID 35401439, 2022). "PAK4 phosphorylation on CEBPB or Integrin β5 promotes the migration and invasion of breast cancer cells." (PMID 36230657, 2022). "Recently, studies have reported that some PAK4 molecular inhibitors, LCH-7749944, FRAX1036, and GNE 2861, showed inhibitory effects in melanoma cells, colon cancer cells, breast cancer cells, and gastric cancer cells." (PMID 34912075, 2022). "And we found that PF-3768309, the small molecule inhibitor of PAK4, combined with ORFV in the treatment of breast cancer can exert a stronger anti-tumor effect." (PMID 35401439, 2022). "In summary, we have clarified the oncolytic effect of ORFV on breast cancer, and found that the combination of ORFV and PAK4 inhibitor can effectively improve the oncolytic effect of ORFV." (PMID 35401439, 2022). "Collectively, our results suggest that methylation of PAK4 at K473 by SETD6 tunes the adhesion, migration and invasion properties of breast cancer cells." (PMID 33051544, 2020). "Since PI3K/AKT signaling has been found activated in NIH3T3 cells overexpressing PAK4 and in pancreatic cancer cells, we attempted to determine the effect of PAK4 on PI3K/AKT signaling in breast cancer cells." (PMID 28407679, 2017). "PAK4 levels are high in MDA-MB-468, SUM159, BT-549 and MDA-MB-231 (all triple negative), MCF7 (ER+/PR+), SkBr-3 (HER2+), and BT-474 (PR+/HER2+) breast cancer cell lines." (PMID 28198380, 2017). "Taken together, these findings suggest that PAK4-activated PI3K/AKT signaling is both kinase-dependent and -independent, which contributes to breast cancer progression." (PMID 28407679, 2017). "Additionally, CEBPB regulates breast cancer cell migration and invasion through diverse pathways, including THBS2 suppression, the PAK4–CEBPB–CLDN4 axis and the cAMP/AMPK/CEBPB axis." (PMID 38982317, 2024). "Furthermore, PAK4 phosphorylates Runt-related transcription factor 1 (RUNX1), a regulator of the DNA damage response in breast cancer cells." (PMID 35883575, 2022). "Here, we find that PAK4 phosphorylates RUNX1, which upregulates downstream genes related to osteoclast differentiation and maturation, including Jagged-1,IL-1α,IL-1β,IL-6 and PTHrP in breast cancer cells." (PMID 32549768, 2020). "To this end, we developed a mouse model with PAK4 overexpression in the mammary epithelium under the control of the MMTV-LTR (mouse mammary tumor virus long terminal repeat) promoter, mimicking the PAK4 overexpression found in breast cancer." (PMID 32158912, 2020). "Nevertheless, the relationship between PAK4 and RUNX1 in breast cancer is still unclear." (PMID 32549768, 2020). "We suspect that the PAK4 phosphorylation of ERα may take place in the cytoplasm, and this phosphorylation is weaker than the PAK1-mediated ERα-Ser305 phosphorylation in breast cancer." (PMID 30177834, 2019). "PDCs were also sensitive to PAK4 abrogation ex vivo while primary non-immortalized HMECs were not, reemphasizing the notion of PAK4 as a potential breast cancer treatment target." (PMID 31399573, 2019). "PAK4 overexpression abrogates OIS in untransformed human mammary epithelial cells (HMECs), leads to mammary tumors in mice and suppresses senescence-like growth arrest in various breast cancer models, controlled by a PAK4–RELB–C/EBPβ regulatory axis." (PMID 31399573, 2019).
breast cancer (continued). "Additionally, a quantitative proteomics analysis of CY-9d-treated breast cancer cells revealed some potential Raf1 and ERK1 interacting proteins in breast cancer cells, such as HSP90, PAK4 and RAB2A." (PMID 29262632, 2017). "Finally, some potential Raf1 and ERK1 interacting proteins in breast cancer cells were detected, such as HSP90, PAK4 and RAB2A." (PMID 29262632, 2017). "Previous studies on the mechanism of PAK4-enhanced tumor progression addressed several downstream effectors, such as c-Src, MEK-1/ERK1/2, MMP2, and c-Src/EGFR in ovarian cancer, p57Kip2 and integrin αvβ5 in breast cancer." (PMID 28407679, 2017). "Meanwhile, we found that both PAK4 and P54 increased gradually as breast cancer progressed (advanced invasive > early invasive > noninvasive)." (PMID 27297086, 2016). "Expression of PAK4 in breast cancer was much higher than that in breast fibroma, and we found that PAK4 increased gradually as breast cancer progressed (advanced invasive > early invasive > noninvasive)." (PMID 27297086, 2016). "In U2OS osteosarcoma and MCF-7 breast cancer cell lines, PAK4 depletion did not affect collective cell migration, but affected cell polarization." (PMID 26068882, 2015). "Thus, no consistent correlation was detected between the expression of PAK family members other than PAK4 (PAK1, 2, 3, 5, 6) and the patient outcome of endocrine treated breast cancer patients in the two databases." (PMID 26554417, 2015). "Interestingly, analysis of data from ER+ breast cancer patients in the Metabric database shows a positive correlation between ESR1 and PAK4 gene expression, which is consistent with an ERα regulation of the PAK4 gene in breast cancer." (PMID 26554417, 2015). "Block of PAK4 also significantly decreased EdU incorporation in MCF-7 breast cancer cells both in the presence and absence of E2 stimulation." (PMID 26554417, 2015). "Importantly, while PAK4 overexpression promoted tamoxifen resistance in MCF-7 human breast cancer cells, pharmacological treatment with a group II PAK (PAK4, 5, 6) inhibitor, GNE-2861, sensitized tamoxifen resistant MCF-7/LCC2 breast cancer cells to tamoxifen." (PMID 26554417, 2015). "Importantly, using a specific PAK4 inhibitor (LCH-7749944) effectively reversed the increased migration and enhanced collagen I adhesion observed in MDA-MB-231 cells following exposure to RBCs from metastatic breast cancer patients." (PMID 40301999, 2025). "Five of the 14 diabetes-related genes, FOXA1, KIF22, PAK4, MTA3, and FGFR3, were specifically highly expressed in only the ER+/PR+ and ER+/PR− subtypes but not ER−/PR+ and ER−/PR− through an analysis using 4032 patient tissue samples from Breast Cancer Gene Expression Miner v4.5." (PMID 39000600, 2024). "Previous studies identified the nuclear PAK4 promotes bone metastasis in ERα positive breast cancer by targeting LIFR 10 and we demonstrated that MCF-7 cells overexpressed PAK4 promote metastatic bone colonization in mice, although MCF-7 was known as a low metastatic potential breast cancer cells." (PMID 32549768, 2020). "PAK4, a kinase that can phosphorylate MZF1 serine 27 in response to ErbB2 activation, is considered as a good target for the treatment of a variety of solid cancers including breast cancer, and its inhibition for this purpose has been patented by Hoffman-La Roche and Genentech." (PMID 31963147, 2020). "However, expression levels and copy number variation of PAK4 in relation to breast cancer patient outcome has not yet been examined in more general and larger sets of breast cancer patients." (PMID 31399573, 2019). "Second, PAK4, as a negative regulator of ERα transactivation functions, might contribute to the aggressiveness of breast cancer cells by allowing the development of ERα-negative phenotypes." (PMID 30177834, 2019). "PyMT mice lacking PAK4 developed mammary tumors significantly later than control mice." (PMID 31399573, 2019).
breast cancer (continued). "This implies that MMTV-Cre induced gene depletion of PAK4 in mice does not impair normal mammary gland development and thereby provides an in vivo model that can be explored for examination of the potential function of PAK4 in breast cancer." (PMID 31594963, 2019). "These correlations were only apparent in breast cancer but not in normal breast tissue, adding to the notion that it may be possible to selectively target the addiction to PAK4 of cancer cells." (PMID 31399573, 2019). "Thus, our results imply that dual inhibition of PAK4 and PI3K/AKT signaling might be a potential therapeutic approach for breast cancer therapy." (PMID 28407679, 2017). "However, while high PAK4 expression displayed consistent correlation with poor outcome of endocrine treated breast cancer patients in two distinct large databases, no other PAK member displayed such a consistent correlation with the patient outcome." (PMID 26554417, 2015). "Here we identify PAK4 as an attractive breast cancer drug target candidate given its overexpression in breast cancer patients negatively affecting prognosis and its key function in evading senescence-like growth arrest in breast cancer cells via the noncanonical NF-κB component RELB." (PMID 31399573, 2019). "We also found in a nude mouse xenograft model that non-aggressive MCF-7 breast cancer cells with high bone metastatic potential expressed higher levels of PAK4 with E2 stimulation, which may enable these cells to alter the expression of downstream ERα target genes." (PMID 30177834, 2019). "Importantly, PAK4 prevents senescence-like growth arrest in breast cancer cells in vitro, in vivo and ex vivo, but is not needed in non-immortalized cells, while PAK4 overexpression in untransformed human mammary epithelial cells abrogates H-RAS-V12-induced senescence." (PMID 31399573, 2019). "Investigation of additional breast cancer cells will help to determine whether the different responses we observed were in fact related to the backgrounds of the different cell types, and whether or not they are related to PAK4 status." (PMID 28198380, 2017). "However, given that ERα Ser305 phosphorylation can be mediated by at least also PAK1, a group I PAK member, and by PKA, the relative importance of these kinases in breast cancer remains unclear, considering also that both PAK1 and PAK4 have been found overexpressed in human breast cancer." (PMID 26554417, 2015).
pancreatic cancer (35 papers, 2014 to 2025). "Knockout of PAK1 and PAK4 suppressed pancreatic tumour growth, which was associated with a reduction in tumour vascularisation." (PMID 40943273, 2025). "Another gene whose overexpression is associated with pancreatic cancer is P21-activated kinase 4 (PAK4), which is associated with increased proliferation, survival, migration, and metastasis of these tumor cells." (PMID 37287924, 2023). "On the contrary, lower PAK4 expression was associated with worse prognosis in pancreatic carcinoma and endometrial cancer." (PMID 37761312, 2023). "PAK4 gene amplification has been most frequently observed in multiple cancer such as oral squamous-cell carcinoma, pancreatic cancer and colon cancer, and is associated with aggressive disease and poor prognosis in oral squamous-cell carcinoma." (PMID 28407679, 2017). "Pancreatic cancer is often associated with increased levels of Pak4." (PMID 34944073, 2021). "Considering the fact that K-Ras is mutated in ~95 % cases of pancreatic tumors, PAK4 might also be involved in mediating and/or regulating constitutive K-Ras activation-driven downstream signaling pathways involved in cell proliferation, survival and therapy resistance." (PMID 25238288, 2014). "Knockout of PAK1 or PAK4 suppressed pancreatic tumour growth in a syngeneic mouse model, demonstrated by reduced tumour volume and tumour weight." (PMID 40943273, 2025). "The individual roles of PAK1 and PAK4 in pancreatic tumour biology are increasingly recognised, yet their distinct contributions to vascular regulation and chemotherapy response remain underexplored." (PMID 41228228, 2025). "Future studies integrating in vivo perfusion and pimonidazole assays will be valuable to validate the functional consequences of PAK1 or PAK4 modulation on vascular normalization and hypoxia in pancreatic cancer models." (PMID 41294859, 2025). "P21-activated kinases (PAKs) are key regulators of the cellular and immune system, but the specific roles of PAK1 and PAK4 in pancreatic tumour vasculature and chemotherapy sensitivity are unclear." (PMID 41228228, 2025). "Knockout of PAK1 or PAK4 increased the pericyte coverage in pancreatic tumour tissues by increasing the ratios of NG2 to CD31 and of α-SMA to CD31." (PMID 40943273, 2025). "PAK1 and/or PAK4 are overexpressed in pancreatic cancer and play a crucial role in its progression, becoming a potential therapeutic target." (PMID 41294859, 2025). "Previous studies have demonstrated that PAK1 and PAK4 contribute to pancreatic cancer progression through diverse mechanisms, including the regulation of proliferation, angiogenesis, and immunity." (PMID 41294859, 2025). "The inhibition of PAK1 or PAK4 suppresses pancreatic cancer by stimulating anti-tumour immunity through the activation of T cells and dendritic cells through ICAM-1 and VCAM-1 upregulations." (PMID 41294859, 2025). "Recent emerging evidence has also pointed to a role of PAK4 in cancer immune evasion in melanoma, prostate cancer, and pancreatic cancer." (PMID 39941877, 2025). "In pancreatic cancer, PAK2 and PAK4 alterations were linked to significant differences in survival outcomes." (PMID 39756822, 2025). "Among the six members of the PAK family, PAK4 has attracted increasing recognition for its role in pancreatic cancer tumorigenesis." (PMID 39941877, 2025). "Together, these results highlight the mechanisms through which PAK1 and PAK4 regulate the vasculature in pancreatic cancer, offering opportunities to exploit their differential functions for tailored therapeutic strategies." (PMID 41294859, 2025). "Supportively, PAK4 inhibition reversed the cisplatin resistance of non-small cell lung cancer cells and sensitized pancreatic cancer cells to gemcitabine and multiple chemotherapeutic agents." (PMID 39273017, 2024). "In pancreatic cancer, PAK4 maintains stem cell-like phenotypes and decreases chemosensitivity to gemcitabine toxicity by activating STAT3 signaling." (PMID 38238316, 2024).